CLK1 (CDC like kinase 1)
Diseases named in the same sentence as CLK1 in open-access papers (continued):
Sharing a sentence is not in itself a finding about the gene and the disease.
embryonal carcinoma (1 paper, 2023). A non-seminomatous malignant germ cell tumor characterized by the presence of large germ cells with abundant cytoplasm resembling epithelial cells, geographic necrosis, high mitotic activity, and pseudoglandular and pseudopapillary structures formation. "Mammalian CLK1 was identified using a phosphotyrosine antibody screening approach on a cDNA expression library, followed by validation of mRNA transcript levels from mouse embryonic carcinoma cells." (PMID 37607329, 2023). "Consistent with a role for CLK in neural development and differentiation, CLK1 mRNA was found to be increased during retinoic acid‐mediated neuronal/astroglial differentiation of the mouse embryonal carcinoma cell line P19 but decreased during differentiation into cardiac and skeletal muscle." (PMID 37607329, 2023).
esophageal cancer (1 paper, 2021). A primary or metastatic malignant neoplasm involving the esophagus. "Survival analysis showed that the higher the expression of CLK1 in esophageal cancer tissues is, the worse the prognosis of patients; the lower the expression of POP7 is, the worse the prognosis of patients." (PMID 34568328, 2021). "Our results revealed that the level of CLK1 mRNA in esophageal cancer is relatively low." (PMID 34568328, 2021). "Survival analysis showed that the higher expression of CLK1 in esophageal cancer tissue is, the worse prognosis of patients, suggesting that CLK1 may play a role in promoting esophageal cancer." (PMID 34568328, 2021). "Survival analysis reveals that a higher expression of CLK1 predicts a significant worse prognosis, and a lower expression of POP7 predicts a worse prognosis in esophageal cancer." (PMID 34568328, 2021). "Consistent with our previous results, compared with non-cancerous tissues, CLK1 mRNA levels are lower in esophageal cancer, and POP7 mRNA levels are higher." (PMID 34568328, 2021). "Our focus was on the expression of CLK1 and POP7 in esophageal cancer." (PMID 34568328, 2021). "At present, no research focuses on the relationship between CLK1 and esophageal cancer." (PMID 34568328, 2021). "Our results show that the level of POP7 mRNA in esophageal cancer is relatively higher, and the lower expression of CLK1 is, the worse prognosis of patients in esophageal cancer, suggesting that POP7 may play a role in promoting progression of esophageal cancer." (PMID 34568328, 2021). "First, the expressions of CLK1 and POP7 were compared in 28 pairs of primary esophageal cancer and non-cancerous tissues from the cDNA array." (PMID 34568328, 2021).
hepatocellular carcinoma (1 paper, 2022). A malignant tumor that arises from hepatocytes. "The circ-CLK1 in this study was reported to play a vital role in hepatocellular carcinoma." (PMID 35156507, 2022).
Insulin resistance (1 paper, 2021). Increased resistance towards insulin, that is, diminished effectiveness of insulin in reducing blood glucose levels. "In summary, the present study provides evidence that knockout or inhibition of CLK1 will prevent obesity and improve insulin resistance." (PMID 34526909, 2021). "In addition, genetic knockout of CLK1 or chemical inhibition in mice ameliorated diet-induced obesity and insulin resistance at 22°C." (PMID 34526909, 2021).
kidney tumors (1 paper, 2016). "Using RNA-Seq data from the Cancer Genome Atlas (TCGA) we observe that CLK1 displays significantly higher expression in 72 kidney tumors compared to matched normal tissue samples (p=10-5, Kolmogorov-Smirnov test)." (PMID 27015110, 2016). "(G) Kaplan-Meier plot showing survival differences between patients with kidney tumors with high CLK1 (red, upper quartile) or reduced CLK1 (blue, lower three quartiles) expression." (PMID 27015110, 2016).
liver cancer (1 paper, 2022). An epithelial or non-epithelial malignant neoplasm that arises from the liver. "Here, we predicted the target miRNA of circ-CLK1 to obtain miR-18b-5p, which has a regulatory effect on ovarian and liver cancer, but has not been reported in OSCC." (PMID 35156507, 2022).
muscular dystrophy (1 paper, 2022). Muscular dystrophy (MD) refers to a group of more than 30 genetic diseases characterized by progressive weakness and degeneration of the skeletal muscles that control movement. "CLK1 has been reported to play a role in cancer due to the associations among CLK1, ASF/SF2, and SRp20 and in muscular dystrophy." (PMID 35565529, 2022).
myeloma (1 paper, 2014). "Chromosomal segments containing genes such as LYST, CLK1, ACSL1 and NFKB1A were amplified in more than 40% of myeloma patients in this study." (PMID 24690091, 2014).
Obesity (1 paper, 2021). Accumulation of substantial excess body fat. "We further showed that CLK1 deficient mice were resistant to HFD-induced obesity under regular room temperature conditions." (PMID 34526909, 2021). "The underlying mechanisms of the reversed phenotype on obesity between CLK1 and CLK2 are unknown and will be further explored in future studies." (PMID 34526909, 2021). "Unlike the phenotype of the Clk1 knockout mice reported here, overexpression of CLK2 in the mediobasal thalamus can partially reverse the HFD-induced obese phenotype in mice, and mice lacking Clk2 in adipose tissue exhibited exacerbated obesity." (PMID 34526909, 2021).
oral squamous cell carcinoma (1 paper, 2022). "This study aimed to explore the role of circular-CDC like kinase 1 (circ-CLK1) in the pathogenesis of oral squamous cell carcinoma (OSCC)." (PMID 35156507, 2022).
schizophrenia (1 paper, 2020). A major psychotic disorder characterized by abnormalities in the perception or expression of reality. "Findings indicated the possible involvement of CLK1 (2q33.1) in perceptual aberrations and schizophrenia, a gene previously associated with breast cancer." (PMID 32152294, 2020).
tauopathies (1 paper, 2014). "However, the dual Dyrk1A/Clk1 inhibitory activity might even provide higher efficacy for the treatment of tauopathies, because both kinases are modifying the pre-mRNA splicing to generate tau species with enhanced pathogenic potential." (PMID 24676346, 2014).
cancer (43 papers, 2015 to 2026). A tumor composed of atypical neoplastic, often pleomorphic cells that invade other tissues. "The elevated expression of these splicing regulators, such as Clk1 and Clk3, helps cells adapt through the AS of key cancer-associated genes." (PMID 37658940, 2023). "CLK1 disruption leads to multiple cell cycle defects and loss of proliferation, whereas the opposite is associated with a variety of cancers." (PMID 34037780, 2021). "Disruption of CLK1 causes pleiotropic cell cycle defects and loss of proliferation, whereas CLK1 over-expression is associated with various cancers." (PMID 27015110, 2016). "(H) Number of cancer-associated AS events that are also regulated by CLK1 in different tumor types." (PMID 27015110, 2016). "Morpholino-mediated depletion of CLK1 exon 4 splicing reduced RNA expression, protein abundance, and cell viability with concurrent differential expression of 78 cancer genes and differential splicing at functional sites in 193 cancer genes." (PMID 39149264, 2025). "Typically, CLK3 is expressed in male testes and sperm, by contrast, as a potential cancer treatment target, the expression level of CLK1 in testicular tissue is significantly lower than other isoforms." (PMID 40599151, 2025). "Numerous studies have reported that Dyrk1A, Dyrk1B, and Clk1 are overexpressed in multiple cancers, suggesting a role in malignant disease." (PMID 38893153, 2024). "In cancer, the overexpression of Clk1 results in the increased subcellular localization of SR proteins, increasing their concentration in the nucleus, which leads to aberrant alternative splicing producing pro-oncogenic variants and antiapoptotic proteins." (PMID 38893153, 2024). "Top up-regulated genes related to cancer were: (i) IL-20, CLK1, SORBS2, ERG1, PIM1, SNORD3A for normal FHC cells and (ii) TSLP, BHLHA15, LAMP3, ZNF27B, KRT17, ATF3 for cancerous HT29 cells." (PMID 38033043, 2023). "While PANC-1 cells exhibited the highest level of CLK1, BxCP-3 cells showed the lowest level of CLK1 among these cancer cell lines." (PMID 33849617, 2021). "Aberrant phosphorylation of splicing factors by CLK1 has been demonstrated to be critically involved in disorders of AS events in human diseases including cancer." (PMID 33849617, 2021). "Upregulation of CLK1–4 expression levels was reported in multiple cancer types, including breast, colon, renal, and lung carcinomas." (PMID 34092037, 2021). "The same holds true for SPF45, an important substrate of CLK1 involved in splicing which is found to be overexpressed in many cancer cell lines." (PMID 29723265, 2018). "Being the most promising compound in terms of CLK1 inhibitory potency and selectivity, KuWal151 (8c) was tested in the National Cancer Institute cancer cell line screening on 57 tumor cell lines of different tissue origin." (PMID 29723265, 2018). "Additionally, we identified transcriptional dysregulation of essential cancer genes mediated by increased CLK1 exon 4 inclusion." (PMID 39149264, 2025). "Interestingly, kinase activation of CLK1 has been observed in various cancer types where it correlates with worse prognosis, but skipping of exon 4 prevents CLK1 from being activated." (PMID 41273175, 2025). "Noteworthy, it has been previously reported that Dyrk1A/Clk1 co-inhibition increased the efficacy of pre-mRNA splicing modulation, which could correct the abnormal splicing examined in cancer." (PMID 38893153, 2024). "Collectively, the strategy of targeting Dyrk1A, Dyrk1B, and Clk1 simultaneously with a small molecule could offer significant benefits in tackling the complex nature of cancer." (PMID 38893153, 2024). "In addition, CLK1 was considered to participate in the onset, progression, and evolution of cancers through different mechanisms, however, the function probably was cancer specific." (PMID 37029108, 2023).
cancer (continued). "Notably, CLK1 intron 4 is variably retained and exon 4 largely excluded, also in a subset of human cancer cell lines and this regulation is reverted by stress conditions." (PMID 34092037, 2021). "Targeting the kinase activity of CLK1 was suggested to be a therapeutic approach in cancer therapy." (PMID 32503434, 2020). "The importance of CLK1 for faithful progression through the cell cycle suggests it may play a role the control of cell proliferation in cancer." (PMID 27015110, 2016). "Finally, we asked whether CLK1 exon 4 inclusion levels affect any of the essential oncogenes defined by the pediatric gene dependency maps of the Childhood Cancer Model Atlas33." (PMID 39149264, 2025). "Thus, alteration of this conserved auto‐regulatory mechanism might also contribute to changes in CLK1 expression and activity in cancers." (PMID 34092037, 2021). "Thus, the increased mitotic index of tumours with respect to normal tissue, combined with the higher CLK1 transcript levels, may account for the observed upregulation of this kinase in human cancers." (PMID 34092037, 2021). "Besides, quercetin could inhibit the activities of many kinases implicated in cancer cell biology, such as ABL1, Aurora-A, -B, -C, CLK1, FLT3, JAK3, and MET." (PMID 31998395, 2019). "We identify and experimentally characterize CLK1 as a candidate oncogenic dependency in pediatric HGGs and propose that targeting of aberrant splicing and/or its resulting downstream proteins may offer additional therapeutic avenues for precision cancer therapy." (PMID 39149264, 2025). "CLK1 and CLK2 are upregulated in various cancers including breast, colorectal, prostate, and glioblastoma." (PMID 38753413, 2024). "The 6 up-regulated genes (IL-20, CLK1, SORBS2, ERG1, PIM1, SNORD3A) are involved in cancer development." (PMID 38033043, 2023). "All the most up-regulated genes (IL-20, CLK1, SORBS2, ERG1, PIM1, SNORD3A) are involved in cancer development." (PMID 38033043, 2023). "CLK1 regulates expression of the alternative splicing factor 45 (SPF45), which is frequently overexpressed in cancer." (PMID 33066143, 2020). "Consistent with the modulation of SP45 activity by CLK1 and earlier findings that CLK inhibitors induce apoptosis and show antitumor activity in vitro, 4 inhibited the growth of certain cancer cell lines at submicromolar concentrations." (PMID 29723265, 2018). "CLK3 is best known for its expression in normal testis; however we suggest that along with CLK1, CLK3 might contribute to adaptation to hypoxia in cancer cells." (PMID 29606096, 2018).
tumor (30 papers, 2010 to 2026). "Clinically, high CLK1 was associated with increased tumor mutational burden and greater sensitivity to chemotherapy." (PMID 41737282, 2026). "Univariate analysis showed that the increased CLK1 expression indicated by IHC was associated with tumor size, lymphatic metastasis, and TNM stage." (PMID 33849617, 2021). "Those CLK1-associated signaling pathways regulate cell migration and invasion are linked to tumor development and progression." (PMID 34526909, 2021). "Moreover, we also found that CLK1 overexpression caused the transition of BxPC-3 cells to spindle-shaped mesenchymal cells, while the adhesion between the tumor cells was enhanced." (PMID 33849617, 2021). "High CLK1 expression correlated with prolonged survival, suppressed cell cycle and metabolism pathways, and enhanced anti-tumor immunity-particularly CD4+ T cell infiltration." (PMID 41737282, 2026). "This inherent variability of CLK1 exon 4 inclusion empowered us to investigate its role in tumor biology." (PMID 39149264, 2025). "Cdc2‐like kinase 1 (CLK1) promotes residual tumor cell survival, and CLK1 suppression enhances the sensitivity to cGAS inhibitors by decreasing proliferation‐associated nascent RNAs." (PMID 38145335, 2024). "Our Dyrk1/Clk1/Haspin inhibitors showed very low toxicity against proliferating non-tumor cells, in contrast to many chemotherapeutic agents." (PMID 38893153, 2024). "The expression of circ-CLK1 in our collected samples and OSCC cell lines was abnormally increased, and inhibition of circ-CLK1 in vitro promoted tumor cell apoptosis and reduced OSCC cell viability." (PMID 35156507, 2022). "At genome‐wide level, CLK inhibitors modulated a subset of AS events that are dysregulated across tumour types displaying CLK1 upregulation, suggesting their efficacy in reverting CLK‐mediated oncogenic features." (PMID 34092037, 2021). "CLK1 expression was scored as high in 112 (60.2%) and low in 74 (39.8%) samples, and tumor tissues had significantly higher CLK1 expression than normal tissues." (PMID 33849617, 2021). "We found that the level of phosphorylated SRSF5 elevated in tumor tissues with a high expression level of CLK1 by IHC." (PMID 33849617, 2021). "For example, one of the strongest tumor-specific hypermethylated signals on chromosome 2 was located in the promoter or the intron of CDC-like kinase 1 (CLK1) transcripts." (PMID 32194853, 2020). "HNRNPH1 and CLK1, two trans-acting splicing regulator factors, are predicted by our computational analysis to be differentially spliced between tumor cells." (PMID 20700505, 2010). "Moreover, Cdc2‐like kinase 1 (CLK1) is critical for residual tumor cell survival after treatment with cGAS inhibitors, and CLK1 suppression enhances sensitivity to cGAS inhibitors." (PMID 38145335, 2024). "The cGAS‐STING pathway is oncogenic in PTCL, whereas targeting cGAS suppresses tumor growth, and CLK1 may be a sensitivity indicator for cGAS inhibitors." (PMID 38145335, 2024). "In addition, miR-18b-5p expression was significantly decreased in UM1 and HSC-2 cells, while it was increased in circ-CLK1 knockdown tumor cells." (PMID 35156507, 2022). "At 4 weeks after tumor cells inoculation, mice injected with CLK1 overexpressing cells exhibited enhanced lung metastasis, as evidenced by bioluminescence imaging, while impaired lung metastasis was observed when CLK1 knock-down cells were inoculated." (PMID 33849617, 2021). "Moreover, the overall survival rate for patients with a high CLK1 expression in tumor tissues was significantly lower than that for patients with a low CLK1 expression." (PMID 33849617, 2021). "Finally, the CLK1-specific inhibitor, CTX-712, is in Phase 1/2 trial for relapsed or refractory AML and high risk MDS47, underscoring CLK1 and its family as a target across diverse tumor histologies." (PMID 39149264, 2025).
tumor (continued). "CLK1 encodes a member of the CDC2-like (or LAMMER) family of dual-specificity protein kinases, which has been found to influence almost all the aspects of tumor biology including: angiogenesis, apoptosis, cell cycle control, invasion, metastasis, and metabolism." (PMID 40831924, 2025). "Notably, the PDAC patients at stage III had significantly more cases of tumor tissues with CLK1-high expression, while the difference in CLK1 expression levels (high vs low) was not obvious in the patients at stage II." (PMID 33849617, 2021).
infection (5 papers, 2015 to 2024). The state of being infected such as from the introduction of a foreign agent such as serum, vaccine, antigenic substance or organism. "Therefore, the mechanism used by Clk1 to modulate L. pneumophila growth and whether Clk1 is ubiquitinated by LubX under infection conditions as well as the consequences of modification remain to be clarified." (PMID 29376029, 2017). "Because of the incomplete inhibition observed with the CLK1 inhibitor KH-CB19 at early times p.i., we were not able to precisely determine the step of infection controlled by CLK1." (PMID 27177310, 2016).
CLK1 also shares sentences with these, for which no sentence is quoted: 3MC syndrome (4 papers); Disseminated intravascular coagulation (3); infectious disease (2); kidney cancer (2); acute kidney injury (1); acute myeloid leukemia (1); Arthritis (1); asthma (1); bacterial infection (1); bladder urothelial carcinomas (1); brain cancer (1); central nervous system tumors (1); COVID-19 (1); cystic fibrosis (1); degenerative diseases (1); dysautonomia (1); dyslipidemia (1); esophageal squamous cell carcinoma (1); gastric tumor (1); genetic disorder (1); hematological cancers (1); hematological malignancies (1); immune complex diseases (1); immune diseases (1); intellectual disabilities (1); invasive breast carcinoma (1); ischemia (1); knee osteoarthritis (1); legionellosis (1); lymphoma (1).
A further 13 diseases each share a sentence with CLK1 in 1 paper.